LOX (lysyl oxidase)
Diseases named in the same sentence as LOX in open-access papers (continued):
Sharing a sentence is not in itself a finding about the gene and the disease.
cancer (continued). "Thus, we innovatively explored the relationship between CAFs and LOX, finding that LOX may be a key factor in CAFs to remodel ECM through collagen crosslinking, and then promote cancer progression." (PMID 34930321, 2021). "The results showed that 8 signaling pathways involved in ECM- receptor-interaction, pathways in cancer, Hedgehog signaling, TGF-beta signaling, JAK-STAT signaling, MAPK signaling, Wnt signaling, mTOR signaling were differentially enriched in the highly expressed phenotypes of LOX." (PMID 34595188, 2021). "Therefore, LOX, MMP-2, and MMP-9 are highly expressed in many malignant tumors." (PMID 31777578, 2019). "Moreover, our analysis indicates that LOX is likely co-expressed with MMP2, COL1A1 and SPARC, all of which contribute to initiating cancer metastasis and EMT, and that bisphosphonates inhibit MMP2 activity, COL1A1-driven osteoporotic fracture and SPARC-stimulated EMT." (PMID 27147578, 2016). "In addition, data mining results from The Comparative Toxicogenomics Database indicates that bisphosphonate down-regulates expression of LOX, MMP2, COL1A1 and SPARC, which means bisphosphonate may suppress cancer metastasis by targeting these four genes." (PMID 27147578, 2016). "HIF-1α enhances the hepatic inflammation, fibrosis and cancer by inducing its target genes such as vascular endothelial growth factor, plasminogen activator inhibitor-1, prolyl 4-hydroxylase, alpha peptide 1 (P4HA1), lysyl oxidase (LOX) and endoplasmic reticulum oxidoreductin 1-like (ERO1L)." (PMID 26098428, 2015). "While studies showed in some cancer cells, after using the COX and LOX inhibitor, GLA or DGLA only led to a partially growth inhibition of cancer cells, which indicates that the change ratio of PGE1/PGE2 derived from DGLA metabolites couldn't completely account for the antitumor effect." (PMID 22333072, 2012). "In addition, lysyl oxidase (LOX) enzymes, also found enriched in hypoxic sEVs, catalyze an important step of the crosslinking of collagen and also elastin, increasing the stiffness of the ECM and thereby facilitating cancer cell adhesion and invasion into the ECM." (PMID 32709110, 2020). "In all three cancer cell lines, Western blot analysis showed a decrease of p-H3, cyclin B1, and AURKB, 72 hr after LOX knockdown, but not with BAPN treatment." (PMID 27296552, 2016). "However, the effect of SHMT2 inhibition appears to depend on the cancer phenotype, in view of the suppression in cell proliferation of rapidly-proliferating LOX IMVI and HeLa cancer cells but not of the slowly-proliferating A498 cell line." (PMID 27391339, 2016). "Furthermore, we demonstrated that the poorly invasive cancer cells HO8910, which express little to no endogenous LOX, aberrantly express high levels of LOX when exposed to hypoxic conditions." (PMID 23545606, 2013).
infection (28 papers, 2009 to 2025). The state of being infected such as from the introduction of a foreign agent such as serum, vaccine, antigenic substance or organism. "Lipid mediator profiling of infected calves suggested the generation of several key oxylipids, produced through catalyzation by COX-1, COX-2, and LOX, across the different infection protocols." (PMID 38543727, 2024). "Changes in the expression of the LOX, ABCA1 and CD36 genes in the CETP mice indicate a possible association between lipid metabolism and the response to infection." (PMID 38966642, 2024). "The action of lipoxygenases (9-LOX and 13-LOX) or α-dioxygenase (α-DOX) initiates the upstream biosynthesis of plant JA, and LOX-derived oxylipins can be involved in the pathogen infection of plants." (PMID 36555209, 2022). "Most genes upstream of JA biosynthesis were highly induced after infection, particularly in Q24, such as the lipoxygenase gene (LOX, Csa7G449420, Csa4G286990), allene oxide synthase (AOS, Csa2G360780), and allene oxide cyclase 2 (AOC2, Csa5G366670)." (PMID 34194451, 2021). "Nevertheless, a statistically significant increase of metabolites of different LOX-pathways was demonstrated for both infection groups." (PMID 31557153, 2019). "After infection, gene expression acted for a more effective recovery, such as the upregulation of LOX genes." (PMID 30237797, 2018). "Recent studies have shown that the LOX gene family in rice plays an important role in blast pathogen infection." (PMID 25935646, 2015). "Likewise, the challenging of chilli plants with B. amyloliquefaciens CRN9 suppressed the infection of GBNV in chilli due to the induction of genes NPR1, PAL, PO, SAR8.2, PDF, LOX, EAS1, and WRKY33 associated with ISR/SAR pathway." (PMID 34946111, 2021). "Therefore, to confirm that strain N1141 possesses ETI-inducible effector proteins, we used qRT-PCR to follow the time course of PAL and LOX gene expression activated by infection with N1141 or NΔT3SS in cultured rice cells." (PMID 28101092, 2016). "Therefore, our results suggest that upon elicitation/infection, VvWRKY1 transcripts accumulate and the VvWRKY1 transcription factor can bind, among others, LOX gene promoters and activate their transcription." (PMID 23342101, 2013). "The KEGG results suggest that up-regulation of LOX, glutathione metabolism, and plant-pathogen interaction, and phenylpropanoid biosynthetic pathways specific to MA-Phy and E14-Phy respectively might contribute to their phenotype after PI infection." (PMID 33297944, 2020). "One LOX (lipoxygenase) gene (comp37329_c0), encoding a critical enzyme in the JA biosynthesis pathway, was highly induced in FW12 and FW48, whereas LTP gene (comp25940_c0) which is necessary in transduction of lipid molecules such as JA was repressed after infection, particularly in FW12 and FW24." (PMID 26849436, 2016). "Compared with unstimulated mock infection, CMV-infected TM cells stimulated by TGF-β1 showed significantly enhanced expression of α-SMA, LOX, CTGF, and fibronectin, which were decreased with additional treatment with 1 μM losartan." (PMID 31216320, 2019). "The expression level of four genes involved in plant defense reactions (LOX, PAL, POX2, and PR1) were assessed during the early stages of treatment as well as infection in order to evaluate the elicitation and priming effects of M1, M2 and GABA on wheat plants against Z. tritici." (PMID 36596821, 2023). "For most biosynthesis genes (OPR and LOX), the basal level of expression was much higher in non-inoculated root tissues compared to non-inoculated spikes which may account for the apparent reduced level of expression of JA-associated processes during infection in roots." (PMID 36352885, 2022). "Also, two LOX genes (PGSC0003DMG400010859 and PGSC0003DMG400024693), and one ACO gene (PGSC0003DMG400013894) were up-regulated at 24 h after CN152 infection in SD20." (PMID 33277549, 2020).
infection (continued). "The decreased level of salicylic acid (SA)-responsive (LOX) and ethylene-responsive (ERF) gene expression in N. benthamiana and A. thaliana supports the notion that ALYs are involved in SA and ethylene-mediated signalling pathways during pathogen infection." (PMID 24723400, 2014). "The heat map showed that a few DEGs, including LOX, OPR, ACX, ACCA1, and MYC2, implicated in JA biosynthesis and signal transduction exhibited higher transcript levels in the OX-CmWD40 line than in the WT both with and without infection A. alternata." (PMID 40163540, 2025). "Finally, in the interaction with the dual infection with both F. poae and F. graminearum neither of the LOX genes was significantly induced." (PMID 33679858, 2021). "However, because the RNAseq experiment included a single time point, it cannot be ruled out that some LOX genes are also responsive to infection with A. flavus at other times." (PMID 28715485, 2017). "The transcript level of LOX (lipoxygenase, D14000) was also not influenced (P>0.05) before bacterial infection, but was 2-fold higher at some time points and 2- to 3-fold lower at other points after pathogen infection in OsDR10-suppressed plants than in wild-type plants." (PMID 19240804, 2009). "We recently reported that expression of PAL and LOX genes are induced in cultured rice cells upon infection by N1141, but not K1, suggesting that PAL and LOX genes are upregulated during ETI." (PMID 28101092, 2016).
cardiovascular diseases (12 papers, 2016 to 2025). "Evidence from human and animal studies suggests that dysregulated LOX/LOXL isoenzyme function or expression has been linked to cardiovascular diseases." (PMID 40332511, 2025). "Abnormal expression and activity of LOX in arterial endothelial cells have been associated with cardiovascular diseases, and LOX plays a role in regulating the proliferation of VSMCs and vascular remodeling." (PMID 39519014, 2024). "Dysregulation of LOX/LOXLs expression/activity has been linked to several human pathologies including cardiovascular diseases." (PMID 31615160, 2019). "Studies in both humans and in animal models have evidenced that the abnormal expression/activity of LOX/LOXLs isoenzymes is linked to cardiovascular diseases." (PMID 31766500, 2019). "LOX and LOXLs control cell proliferation, migration, adhesion, differentiation, oxidative stress, and transcriptional regulation and, thereby, their dysregulation has been linked to a myriad of cardiovascular pathologies." (PMID 31615160, 2019). "The development of LOX/LOXLs-targeted therapeutic tools, however, has been hampered by the unavailability of their crystallographic structure and the fact that both increases and decreases of LOX/LOXLs underlie the development of different cardiovascular diseases that often coexist." (PMID 31615160, 2019). "Regarding the heart, LOX and LOXLs are spatiotemporally regulated during embryonic and fetal heart development, and results in humans and in different experimental models have clearly evidenced that the disturbance of LOX/LOXLs expression/activity is linked to cardiovascular diseases." (PMID 31766500, 2019). "Experimental models have described evidence of the disturbance of LOX/LOXLs activity and cardiovascular diseases." (PMID 38664609, 2024). "As outlined in this review, the impact of LOX/LOXLs dysregulation on the cardiovascular system and its contribution to different cardiovascular disorders support the interest of these enzymes as novel pharmacological targets for these diseases." (PMID 31615160, 2019). "Another issue to be considered is the potential impact on LOX activity of drugs in use for the management of cardiovascular diseases." (PMID 31615160, 2019). "The results show the participation of both PON1 and LOX in the pathogenesis of cardiovascular diseases play a significant role in men with type II obesity." (PMID 31737129, 2019). "This review examines the most recent advances in the study of LOX and LOXLs biology and their pathophysiological role in cardiovascular diseases with special emphasis on their potential as therapeutic targets." (PMID 31615160, 2019). "A first link between the pro-migratory LOX and miR-145-5p has been described only in cardiovascular diseases, but to our knowledge, nothing is known about miR-141-3p or miR-145-5p regulation of LOX in tumors." (PMID 27336447, 2016). "Our data indicate that LOX-induced oxidative stress participates in the procalcifying effects of LOX activity in ectopic cardiovascular calcification, and highlight the multifaceted role played by LOX isoenzymes in cardiovascular diseases." (PMID 38790628, 2024). "LOX and LOXLs control cell proliferation, differentiation, and transcriptional regulation, thereby, alteration has been reported to be related to the onset of cardiovascular diseases." (PMID 33413618, 2021). "It should be highlighted, that the benefit of some drugs widely used for the management of cardiovascular diseases could be derived, at least in part, by their ability to inhibit LOX." (PMID 31766500, 2019). "Furthermore, the LOX index was suggested to be a useful marker for the early diagnosis of cardiovascular diseases." (PMID 28761986, 2018). "Therefore, there may be a close relationship between the LOX index, smoking, and cardiovascular diseases." (PMID 28761986, 2018).
connective tissue disorder (9 papers, 2012 to 2024). A disease involving the connective tissue. "In contrast, OHS is characterized by connective tissue disorders caused by decreased lysyl oxidase activity." (PMID 21838703, 2012). "If the delivery of copper into the trans-Golgi apparatus of affected cells could be achieved, then copper treatment would probably normalize the activity of lysyl oxidase and improve connective tissue disorders associated with MD and OHS." (PMID 21838703, 2012). "Based on these findings, future therapeutics could target LOX-mediated collagen crosslinking to enhance mechanical properties of abnormally weak tendons during treatment of connective tissue disorders and musculoskeletal abnormalities in childhood years." (PMID 35992359, 2022). "LOX and its linked LOX-like (LOXL) isoforms are known to play a major role in ECM remodeling, and their physiological regulation has become an important mechanism implicated in the development of connective tissue disorders, including cardiac tissue fibrosis." (PMID 32824630, 2020).
kidney disease (7 papers, 2018 to 2024). "Genes downregulated by EGCG, especially SLC12A1 or LOX, can be associated with several processes related to renal disease, most significantly “abnormal renal water reabsorption”." (PMID 37627594, 2023). "In a study of 202 kidney disease cases of different etiologies, the levels of serum LOX and tissue LOX in renal biopsies were associated with the presence and degree of kidney fibrosis across diseases (Zhang XQ." (PMID 35237156, 2022). "In cyclosporin A-induced nephropathy in mice, treatment with LOX inhibitors attenuated inflammation, fibrosis and uremia." (PMID 35237156, 2022). "A number of complex, tissue-specific interactions of LOX in relation to vascular, cardiac, pulmonary, dermal, and renal disorders have previously been identified, demonstrating that it can act as both a regulatory target and an active player in multiple signaling pathways." (PMID 39766266, 2024). "The induction of renal lysyl oxidases, in particular LOX and LOXL2 has been shown in several kidney disease models." (PMID 29930330, 2018).
heart disease (5 papers, 2013 to 2025). "Because an increase in collagen cross-links enhances ventricular stiffness and reduces compliance, LOX up-regulation could compromise ventricular function in cardiac diseases and could underlie the alteration of left ventricle relaxation and contraction observed in our study." (PMID 23741440, 2013). "Furthermore, safety concerns should be considered, since increased expression/activity of these isoenzymes has been associated with cardiac diseases, but a decrease of LOX could underlie the development of several vascular pathologies and promote plaque instability." (PMID 31766500, 2019). "Essentially, fibrosis is characteristic of all forms of heart disease, and most of the pathophysiological stimuli that trigger cardiac fibrosis modulate LOX/LOXLs, playing a critical role in the process." (PMID 31766500, 2019). "LOX isoforms could also be assessed for their roles and potential clinical applications in the early diagnosis and management of heart diseases." (PMID 36848364, 2023). "Importantly, lumican and LOX isoenzymes can be upregulated by the release of inflammatory cytokines from leucocytes and altered mechanical stress, both of which are important components of many cardiac diseases, including HCM." (PMID 37443910, 2023). "Key myocardial proteins, lumican, lysyl oxidase (LOX) isoenzymes and TGF-β isoforms are critical for the development of fibrosis and cardiomyocyte hypertrophy in various cardiac diseases." (PMID 37443910, 2023). "As lumican has been reported to promote myocardial ECM remodelling through upregulating LOX and TGF-β in cardiac diseases, the relationship between the lumican gene and these potential downstream targets was assessed." (PMID 37443910, 2023).
adenocarcinoma (3 papers, 2017 to 2022). A common cancer characterized by the presence of malignant glandular cells. "These staining results suggested that modifying enzymes such as hydroxylases and LOX can be enhanced by some oncogenes in adenocarcinoma tissues." (PMID 29072684, 2017).
lung (3 papers, 2007 to 2017). "Whereas G361 and FEMX-1 rarely formed lung metastases, MeWo, MV3 and LOX were moderately and UISO-Mel6 was highly metastatic." (PMID 17262079, 2007).
bacterial infection (2 papers, 2009 to 2019). "The reduced accumulation of JA in OsDR10-suppressed plants was associated with suppressed expression of LOX and AOS2 after bacterial infection, suggesting that OsDR10 is an activator of the JA-dependent pathway and it functions upstream of JA." (PMID 19240804, 2009).
colon polyp (2 papers, 2018 to 2021). "Familial segregation analysis showed that the LOX variant was also present in the father (2-II:1) and in DNA extracted from a colon polyp of the paternal grandfather." (PMID 34281165, 2021).
gastrointestinal disorders (2 papers, 2021 to 2023). "Therefore, LOX inhibitors are potential modulators of such phenomena, and could be of use in the control of inflammation, some gastrointestinal disorders, or adverse cardiovascular reactions." (PMID 33668106, 2021).
hematological malignancies (2 papers, 2020 to 2023). "Dysregulation of fibronectin, collagens, and lysyl oxidase (LOX) leads to BM fibrosis and is a poor prognostic factor and indicator of disease progression in hematological malignancies, particularly MM." (PMID 38002311, 2023).
myopathy (2 papers, 2019 to 2025). A disease of the muscle in which the muscle fibers do not function properly. "Previous studies also reported the upregulation of several genes of collagen crosslinking enzymes, including lysyl oxidase (LOX) in WB myopathy, while results from the present study showed an upregulation of this gene in SM muscles only." (PMID 40841884, 2025). "This formation of aldol cross-links is mediated by lysyl oxidase which can be another target biomolecule to intervene P. major WB myopathy issue." (PMID 31998759, 2019).
skin disorder (2 papers, 2020 to 2022). Any deviation from the normal structure or function of the skin or subcutaneous tissue that is manifested by a characteristic set of symptoms and signs. "The intra- and extra-cellular functions of LOX proteins play a significant role in the normal ageing process of skin as well as several skin disorders." (PMID 32621591, 2020).
LOX also shares sentences with these, for which no sentence is quoted: idiopathic pulmonary fibrosis (8 papers); Marfan syndrome (4); fibrosarcoma (3); Infertility (3); rhabdomyosarcoma (3); squamous cell carcinoma (3); acute myocardial infarction (2); Arthritis (2); atrial fibrillation (2); depression (2); dyslipidaemia (2); head and neck tumors (2); neurological disease (2); oropharyngeal squamous cell carcinoma (2); Peritoneal Fibrosis (2); stomach cancer (2); abdominal aortic aneurysm (1); Achalasia (1); acute myeloid leukemia (1); Aortic root aneurysm (1); aortic valve disease (1); arteriopathies (1); autoimmune myocarditis (1); Barrett esophagus (1); benign ovarian tumor (1); blast (1); brain cancer (1); breast adenocarcinoma (1); brittle cornea syndrome (1); calcific aortic valve disease (1).
A further 78 diseases each share a sentence with LOX in 1 paper.